PPDPFL (pancreatic progenitor cell differentiation and proliferation factor like)
Synonyms: C8orf22
Tractability: No criterion of Open Targets' tractability assessment is met for any kind of drug.
Gene: Protein-coding gene on chromosome 8 (49,054,311 to 49,076,093, forward strand). Ensembl gene ENSG00000168333.
Gene Ontology:
Biological process: cell differentiation
Genetic constraint (gnomAD): Loss-of-function variants: 4 observed, 7.72 expected, observed/expected ratio (o/e) 0.52, 90% interval 0.25 to 1.18. That is too few expected variants to judge how well the gene tolerates losing a copy. Missense variants: 75 observed, 67.72 expected, observed/expected ratio (o/e) 1.11, 90% interval 0.92 to 1.34. Synonymous variants: 15 observed, 23.14 expected, observed/expected ratio (o/e) 0.65, 90% interval 0.43 to 1.
Homologues: Orthologues: chimpanzee PPDPFL (100% identical), macaque PPDPFL (87% identical), rabbit PPDPFL (77% identical), dog PPDPFL (74% identical), zebrafish ppdpfb (31% identical), zebrafish ppdpfa (30% identical). Paralogues in human: PPDPF (33% identical).
Diseases named in the same sentence as PPDPFL in open-access papers:
PPDPFL is named in the same sentence as 2 diseases in open-access papers, as found by Europe PMC text mining. Sharing a sentence is not in itself a finding about the gene and the disease.
PPDPFL shares sentences with these, for which no sentence is quoted: lung adenocarcinoma (1 paper); squamous cell carcinoma (1).